TF (transferrin)
Diseases named in the same sentence as TF in open-access papers (continued):
Sharing a sentence is not in itself a finding about the gene and the disease.
cancer (continued). "Particularly, a prospective cohort study demonstrated an association between MVs TF activity in cancer patients and total mortality and prognosis, but not thrombosis." (PMID 36013171, 2022). "In addition, study has pointed out that TF MYC was usually expressed constitutively in cancer, which led to an increased expression of many genes, some of which were involved in cell proliferation, in turn leading to cancer formation." (PMID 35743172, 2022). "Thus, the functionalization of liposomes with transferrin can enhance the transfection of genes in different cancer cells, including brain tumors, squamous cell carcinoma, hepatocarcinoma, fibrosarcoma, leukemia, cervical cancer, and others." (PMID 35456655, 2022). "we found that ZNF655, a TF, can affect a variety of functions in a variety of cancers." (PMID 35927248, 2022). "These in vitro results confirmed the advantage of using drug delivery systems combined with transferrin targeting ligand, which significantly increased the cellular accumulation and antiproliferative activity of α-mangostin in cancer cells overexpressing Tf receptors." (PMID 36081606, 2022). "Higher transferrin saturation (circulating iron) or serum iron concentration was also associated with increased risk of nonskin-cancer death in a Western Australian population." (PMID 36551774, 2022). "Several other mechanisms of anticancer therapeutic strategies involving the reduction or prevention of iron intake in cancer cells may also be considered through the delivery of other metals closely related to iron, such as gallium, by transferrin." (PMID 36430469, 2022). "It is also induced by TF Snail to promote the collective migration of cancer cells." (PMID 35456223, 2022). "In addition to its presence on cancer cells, TF expression has also seen to be upregulated in stromal components of the TME including endothelial cells and fibroblasts." (PMID 36046842, 2022). "Implications of patient survival in CRC tumors harboring TF expression may be related to cancer immunity." (PMID 33572915, 2021). "In addition, compared to liver metastatic cancer tissues, CP, HP, TF, and SERPINA5 were upregulated in normal liver tissues, while the expression CDH2 and SPARCL1 did not exhibit significant differences between the two tissues." (PMID 34422629, 2021). "Tumor tissue factor (TF) contributes to cancer metastasis in some NSCLC patients." (PMID 33650320, 2021). "Furthermore, the endosomal reductase, STEAP3, has been demonstrated to be highly expressed in cancers, and is thought to reduce transferrin Fe3+ to Fe2+ in the endosome to be exported into the cytosol for cellular use." (PMID 34572031, 2021). "γ-TT was found to decrease TNF-α-stimulated inducible and constitutive NF-κB activation, as well as STAT3 activity and its DNA binding activity in various cancer cell types (in contrast with γ-TF), which was found to be correlated with the inhibition of Src kinase and JAK1 and JAK2 kinases." (PMID 33919211, 2021). "Interestingly, the inhibitory effects of miltefosine on cancer cell viability, sphere formation and stem‐related TF expression were significantly blocked by CHEK1 overexpression." (PMID 34841679, 2021). "Moreover, CDH2, CP and TF were low expressed in primary cancer than normal tissues, but highly expressed in metastatic liver cancer." (PMID 34422629, 2021). "Induction of EMT via the deregulation of LINC-ROR may activate the expression of stemness marker, SALL4, as a TF with an oncogenic role in GC, to promote cancer phenotype." (PMID 33745265, 2021). "The TF expression was detected also in carcinomas with signet ring cells." (PMID 33572915, 2021). "Therefore, transferrin-mediated endocytosis and the subsequent recycling pathway are highly efficient in cancer cells." (PMID 32957689, 2020).
cancer (continued). "Similarly, xenobiotic metals such as platinum (Pt), ruthenium (Ru) and Ga and their complexes which are used in therapeutic strategies primarily against cancer, interact with transferrin and other proteins of iron metabolism and also with chelating drugs." (PMID 32545424, 2020). "We demonstrate the feasibility of facet modulation for enhancing the receptor-mediated cancer cell delivery of cadmium chalcogenide nanocrystals via preferential and stable chemical adsorption of transferrin to specific exposed facets in a complex biological matrix." (PMID 32152269, 2020). "The ability of L1 to remove iron from transferrin may increase the anticancer activity by minimizing cancer cell iron uptake." (PMID 32545424, 2020). "Potentially the most effective is the inhibition of hepcidin production and activity, therapy with transferrin conjugates with anti-cancer drugs, and increasing iron absorption from the gastrointestinal tract and synthesis of erythropoietin using PHD inhibitors and HIF-2 α stabilizers." (PMID 32560029, 2020). "Thus, the peptides are most likely not binding to antigens that are expressed by several different types of cancer, such as the Thomsen–Friedenreich (TF) antigen, galectin-3, or the epidermal growth factor receptor (EGFR)." (PMID 32380649, 2020). "In this case, one can expect that therapeutic agents targeting the GM-CSF/Jak/Stat5β signaling pathway (e.g., GM-CSF neutralizing antibodies or Jak kinase inhibitors) lowers transferrin levels specifically in the neutrophil-dominant metastatic microenvironment and inhibits cancer metastasis." (PMID 33679721, 2020). "Therefore, transferrin saturation is a more reliable marker of bioavailable iron in cancer patients." (PMID 33292849, 2020). "Here we find that pro-inflammatory cytokines participate in the cytotoxic reaction triggered by the conjugate, and this may be associated with the active delivery of a higher DOX dosage to cancer cells via a transferrin-dependent pathway." (PMID 33321722, 2020). "Administration of gatipotuzumab (previously known as PankoMab-GEX), a humanized mAb that binds TA-MUC1 in a Tn/TF-dependent manner, was found safe and was well-tolerated in patients with advanced carcinomas, suggesting a potential pan-carcinoma imaging application of the targeting moiety." (PMID 33371487, 2020). "The loading of plumbagin in transferrin‐bearing liposomes significantly enhanced plumbagin uptake by cancer cells, resulting in an improvement of the antiproliferative (by up to 4.3‐fold) and apoptosis efficacies (by up to 5.5‐fold) compared with the drug solution." (PMID 31341642, 2019). "The entrapment of plumbagin in transferrin‐bearing liposomes led to an increase in plumbagin uptake by cancer cells and improved antiproliferative efficacy and apoptosis activity in B16‐F10, A431, and T98G cell lines compared with that observed with the drug solution." (PMID 31341642, 2019). "Thus, specific ligands (i.e., transferrin, folic acid, monoclonal antibodies, and peptides) able to bind receptors overexpressed on the surface of cancer cells have been coupled on the liposome surface." (PMID 31929800, 2019). "Then the transferrin supplies iron to the cancer cells for their proliferation." (PMID 31474975, 2019). "Importantly, the binding to either HSA or human apo-transferrin is beneficial to the cytotoxicity of the complex towards human cancer cells by enhancing the cytotoxic activity of RuNTF." (PMID 31394747, 2019). "However, decreased serum iron level together with high ferritin in the context of a decreased transferrin saturation is indicative for immune-driven iron sequestration as occuring in inflammation, infection, liver or kidney disease, and cancer." (PMID 30936264, 2019).
cancer (continued). "For specific delivery of liposomes or lipoplexes loaded with siRNA molecules into cancer cells, transferrin may be attached to them to facilitate their binding to cancer cells through transferrin receptor (TfR/CD71) and their active entry into the cells." (PMID 31024572, 2019). "This, in addition to the presence of transferrin and transferrin receptor on cancer derived exosomes, supports the hypothesis that TfR1 plays a role in exosome internalization." (PMID 30405884, 2018). "Not only EVs derived from cancer cells but also EVs from monocytes expose TF." (PMID 30186839, 2018). "This work showed that transferrin led to selective accumulation of ferric ion in cancer cells." (PMID 30202000, 2018). "After confirming that ferric ion selectively accumulated in cancer cells using transferrin injection, we conducted experiments on cancer-bearing mice to confirm whether ferric ion would boost temperature elevation with radiofrequency hyperthermia." (PMID 30202000, 2018). "This work shows that application of transferrin as a thermosensitizer in radiofrequency hyperthermia successfully increased temperature selectively in cancer tissues, allowing the temperature of cancer tissues to increase up to 47 °C while minimally affecting normal tissues." (PMID 30202000, 2018). "Overall, these experiments indicate that ferric ion, selectively accumulated in cancer cells, reacted with the radiofrequency wave to induce dielectric heat more efficiently, suggesting that transferrin would be an ideal choice for radiofrequency hyperthermia as a thermosensitizer." (PMID 30202000, 2018). "Recently, transferrin (Tf)-functionalized gold nanoclusters (Tf-AuNCs)/graphene oxide (GO) nanocomposite (Tf-AuNCs/GO) was manufactured as a turn-on near-infrared (NIR) fluorescent probe which can be utilized for bioimaging of cancer cells and small animals." (PMID 30259230, 2018). "TF-HA-CMC-PLGA NPs enter cancer cells that overexpressed TFR via TFR-mediated endocytosis pathway." (PMID 29209206, 2017). "Cell uptake and ROS generation analysis provided evidence to support the validity that TF-modified nanoparticle could enhance the accumulation of hypocrellin A in TFR positive cancer cells." (PMID 29209206, 2017). "TF-HA-CMC-PLGA NPs is a potential TDDS for cancer therapy in vitro and in vivo." (PMID 29209206, 2017). "The surface modification of NPs with biological ligands, such as folate, arginine-glycine-aspartate (RGD) peptides, aptamers, transferrin, antibodies or small antibody fragments, facilitates NP targeting, imaging and internalization into specific cells, e.g., cancer cells, and tumor tissues." (PMID 28491487, 2017). "Importantly, in all three assays, the drug was used for the first time in in-vitro studies, not in the intact form but as its active species released from the transferrin adduct at simulated cancer cytosolic conditions." (PMID 28116493, 2017). "We concluded the different PDT efficacy in vivo that nanocarrier could improve the water-solubility and bioavailability of HA and TFR-mediated endocytic pathway could improve the cellular uptake of TF-modified nanoparticles within TFR positive cancer cells." (PMID 29209206, 2017). "The protein serotransferrin (TF) was consistently significantly up regulated in all cell lines at both time points as result of low glucose conditions, however, is considered to be of limited use as a cancer specific biomarker." (PMID 28086232, 2017). "In order to further evaluate the role of transferrin in the cellular uptake of TF-8arm-PEG–DHA NPs, LLC cells and MLE-12 cells were employed as transferrin receptor (TFR) overexpressing cancer cells and TFR deficiency cancer cells, respectively." (PMID 27377918, 2016). "In addition, IKZF1 encodes a TF regulating lymphocyte differentiation, and INHBA, which belongs to the TGF-β superfamily, is associated with several cancers." (PMID 27829444, 2016).
cancer (continued). "Thus, the principal roles of transferrin have been shown as a cell growth factor dependent on iron is crucial for the growth of cancer cells." (PMID 26664465, 2015). "Indeed, when analyzing data from cancer TF studies we found that de novo ChIP-Seq analysis performs as well as peak-calling methods, and in some cases it even slightly improves over alignment based methods." (PMID 26400819, 2015). "However, if the element is a competitive alternative to iron onto transferrin inhibits the growth of cancer cells." (PMID 26664465, 2015). "Also, in the presence of transferrin Cerium has a more significant effect on the mortality rate of cancer cells." (PMID 26664465, 2015). "We speculate that encapsulation of artemisinin and transferrin in magnetic nanoliposomes could increase the artemisinin and transferrin stability, whilst improving selective targeting towards cancerous tumors trough magnetic attraction and thermosensivity." (PMID 24887240, 2014). "Holo-transferrin has been suggested as a potential drug carrier and delivery system to allow specific targeting to, for instance, cancer cells, since the TfR is over-expressed in a broad range of cancers." (PMID 22410420, 2012). "Transferrin has also been used for anticancer drug delivery in cancer chemotherapy." (PMID 22069717, 2011). "Specific cancer induced forms of common serum glycoproteins, such as transferrin or haptoglobin that are synthesized mainly in the liver, have also been observed and may serve as markers of the physiological effects of the cancer." (PMID 22028908, 2011). "In conclusion, although we could lay out the partial picture to describe how cerium ion and cerium-transferrin complex have inhibitory activity on cancer cell proliferation, the real mechanism of action remains unclarified." (PMID 21589800, 2010). "Notably, exosomal TF-Ag-α maintained high detection capability for early-stage (I/II) cancers, with 98.3% sensitivity, 100% specificity, and an AUC of 0.999, demonstrating its strong potential for early cancer detection." (PMID 41374931, 2025). "This aspect has great appeal as common features to all cancers are possession of TfR1 receptors, their altered iron metabolism and increased needs for iron to support their rapid growth and their primary dependence on host transferrin as the source of this iron." (PMID 36978919, 2023). "Moreover, we also explored these TF expression levels in pan-cancers." (PMID 36814821, 2023). "As the compendium expression datasets involved our first removing cancer type-specific differences to arrive at our pan-cancer subtypes, this removed lineage-specific TF expression patterns, although such patterns could be observed in the original datasets before normalization." (PMID 36731467, 2023). "TF has also shown as one of the promising markers due to better segregation with high accuracy in ML, and could further be correlated with altered iron metabolism and its link with cancer progression and metastasis." (PMID 37770851, 2023). "In addition, influenced by the activation of receptor GALR2, TF MYOCD is upregulated after the signal is transmitted into the nucleus, which causes the development and differentiation of smooth muscle, indirectly promoting the migration of cancer cells." (PMID 35164166, 2022). "We hypothesized that this drawback could be overcome by loading the drug within a delivery system conjugated to transferrin (Tf), whose receptors are overexpressed on many cancer cells and would enhance the specific delivery of α-mangostin to cancer cells, thereby enhancing its therapeutic efficacy." (PMID 36081606, 2022). "Interestingly, pre-incubation with holo-TF before the VC treatment was more efficient in enhancing cytotoxicity than when added concomitantly, which suggested that intracellular iron content was a critical determinant of the anti-cancer effects of VC." (PMID 36139668, 2022).
cancer (continued). "Similarly, a 2012 study showed that SLN nanoparticles loaded with transferrin-conjugated curcumin could inhibit cancer cells by stopping the cell cycle and increasing the expression of caspase genes, which is similar to the present study." (PMID 35815210, 2022). "In addition, transferrin protein has received major attention in drug targeting to enhance an efficient cellular uptake of transferrin (TF)-modified nanoformulated drugs due to the high expression of transferrin receptors on the surface of cancer cells." (PMID 34069106, 2021). "In addition, transferrin (Tf) receptors are usually overexpressed in cancer cells." (PMID 33650320, 2021). "We believe this hybrid nanoplatform can be a promising drug delivery system for cancer treatment by modifying the transferrin and liposomes with other active compounds, and could easily enable industrial production to meet the criteria for clinical trials due to its simple preparation process." (PMID 34959271, 2021). "There are many targets (such as folate receptors, transferrin (Tf) receptors, antigens) which are usually overexpressed on the surface of cancer cells, and targeting them to maximize the drug accumulation around cancer cells have become a focus research to cancer therapy in recent decades." (PMID 33154350, 2020). "A direct immunoassay of TF expression levels in NAFs of 124 women requiring biopsy because of a suspicious breast lesion demonstrated that TF concentrations in NAFs could distinguish women with precancer and cancer from those with benign disease." (PMID 32992445, 2020). "Consequently, whether iron status (which is routinely measured in clinical practice as serum iron, transferrin saturation, ferritin and transferrin) plays a role in the development of site-specific cancer remains inconclusive." (PMID 32092884, 2020). "Some specific markers are over-expressed on the membranes of cancer cells, such as integrin αvβ3, CD44 and receptors of transferrin, folic acid and galactose, the ligands of which could be grafted onto the surface of gas-releasing nanomedicines to recognize cancer cells." (PMID 34691545, 2020). "Moreover, treatment with either ferrous iron or transferrin can enhance the cytotoxicity of DHA toward cancer cells, which could be reversed by iron chelator or anti-transferrin receptor antibody." (PMID 31519193, 2019). "In light of the EV-mediated transfer of biological molecules, magnet-conjugated transferrin bound to transferrin receptor-expressed blood exosomes has been shown to preferentially target magnets surrounding cancer cells, followed by the inhibition of cancer development." (PMID 31078138, 2019). "Thus, receptor ligands such as transferrin, folic acid, or different monoclonal antibodies raised against tumor-associated antigens (TAA), including receptors, have been largely investigated to target different cancer cells." (PMID 31929800, 2019). "Therefore, targeting this TF may reduce cancer malignancy and improve the oncologic outcome for cancer patients." (PMID 31861725, 2019). "Therefore the role of TF+ EV as biomarker for VTE in cancer patients remains a matter of debate." (PMID 30186839, 2018). "Interestingly, previous studies showed that cancer cells are addicted to high iron levels and accumulate the metal through transferrin-dependent uptake; and the high levels of copper concentrated in cancer cells is presumed to be important in both angiogenesis and metastasis." (PMID 28881661, 2017). "Therefore, these novel formulations could be a promising approach for artemisinin and transferrin targeted cancer therapy." (PMID 24887240, 2014). "Furthermore, ARNT is regulator involved in TF-miRNA feed-forward loop in cancer." (PMID 23293768, 2012).